IDH1 (isocitrate dehydrogenase (NADP(+)) 1)
Diseases named in the same sentence as IDH1 in open-access papers (continued):
Sharing a sentence is not in itself a finding about the gene and the disease.
cancer (continued). "Isocitrate dehydrogenase (IDH) enzymes IDH1 and IDH2 are frequently mutated in several cancers and a gain-of-function activity promotes conversion of α-ketoglutarate (α-KG) to the oncometabolite 2-Hydroxyglutarate (2-HG)." (PMID 36048239, 2022). "Compared with wildtype (wt) IDH1/2 tumours, 10- to 100-fold higher concentrations of D2HG were reported in IDH-mutated cancers." (PMID 35744895, 2022). "IDH1 mutation, detected in 1% of primary PCa, appears also in other cancers, and ongoing trials for IDH1-mutant malignancies highlight its clinical actionability." (PMID 35205640, 2022). "Recent studies have pointed to IDH1/2-mt cancers as vulnerable to higher seizure incidence relative to IDH-wt." (PMID 36643416, 2022). "Both IDH1 and IDH2 mutations have been reported in cancers, whereas usually only one mutation is identified in a certain cancer." (PMID 35814406, 2022). "In the presence of cancer-associated stress (e.g., nutrient limitation), cancer cells are highly dependent on wtIDH1, rendering wtIDH1 inhibition with allosteric IDH1 inhibitors lethal to treated cancer cells." (PMID 36153582, 2022). "Both EZH2 and IDH1 are known epigenetic modifiers that contribute to the “stemness” of cancer through aberrant histone and DNA methylation, leading to the occurrence and progression of malignancies." (PMID 36292072, 2022). "As mutant IDH1/2 are restricted to cancer cells, this effect is very likely secondary to reduction of the oncometabolite." (PMID 36582801, 2022). "In cancer cells, IDH1- or IDH2-mediated carboxylation of α-KG to citrate is crucial for cell growth and viability under hypoxia." (PMID 35762591, 2022). "The impact of IDH1 on cancer cell antioxidant defense was likely attributable to enhanced generation of NADPH related to upregulated IDH1 expression observed with low glucose stress." (PMID 36153582, 2022). "Of the three isoforms of IDH, IDH1/2 appear to have the most relevance to cancer and have therefore been the focus of drug development." (PMID 35406572, 2022). "Inhibition of mutant IDH1 (mIDH1) reduces 2-hydroxyglutarate (2-HG) levels, which induces apoptosis and differentiation of the proliferating cancer cells." (PMID 36160383, 2022). "Among these, six cancers had additional genetic alterations: BRAF fusions (n = 2), and one each with RET fusion plus BRCA2 loss of function mutation, IDH1 mutation, RAF1 fusion, and EML4-NTRK3 fusion." (PMID 36124727, 2022). "If applied early in the treatment of gliomas, IDH1 inhibitors can prevent the spread of the cancer and decrease the potential side effects of radio- and chemo- therapy." (PMID 35802554, 2022). "Here, we demonstrate that Ag120 (ivosidenib), a mutant isocitrate dehydrogenase 1 (IDH1) inhibitor approved for the treatment of certain cancers, acts as an ASCT2 inhibitor in CRC cells." (PMID 35418865, 2022). "Second, preclinical, translational, and clinical studies with mtIDH1/2 inhibitors consistently showed that these agents reverse this stemness and promote cellular differentiation of IDH1/2mt cancer cells." (PMID 34967233, 2022). "According to the RNA-seq of GBM from TCGA, it was detected that the IDH1 was up-regulated in GBM when compared with para-carcinoma tissue." (PMID 35488886, 2022). "This pathway has been implicated in various cancers, e.g., melanoma, colorectal cancer, HER2-positive breast cancer, pancreatic cancer, isocitrate dehydrogenase 1 (IDH1)-wild-type glioma, lung adenocarcinoma, and thyroid carcinoma." (PMID 33920054, 2021). "This work represents an advance in biomedical science because it shows IDH1 and IDH2 mutational spectrum, significant prevalence in large cancer series and benefit of testing them for prognosis and therapeutic management." (PMID 35996504, 2021).
cancer (continued). "Three IDH mutations (IDH1-R132x, IDH2-R172K, and IDH2-R140Q) occur predominantly in subsets of cancers and regulate central circuitry metabolism by producing the oncometabolite, 2-hydroxyglutarate (2-HG)." (PMID 34020723, 2021). "Gain-of-function IDH1 [isocitrate dehydrogenase (NADP(+)) 1] and loss-of-function TET [ten–eleven translocation] mutations have been shown to induce CIMP in one more than one cancer type." (PMID 34074348, 2021). "Through a survey of more than 45,000 pan-cancer samples, we observed that IDH1 and IDH2 hotspot mutations are uncommon (2%) and extremely rare (0.4%), respectively, in human cancer, a finding in agreement with an independent pan-cancer analysis." (PMID 34440884, 2021). "In less than 10 years from the original discovery of cancer-associated IDH1 and IDH2 mutations, first-in-class mutant IDH1 and IDH2 are now clinically available for patients with AML harboring these mutations." (PMID 34083508, 2021). "Many well‐known proteins that play crucial roles in cancer like IDH1, PTEN, and KRAS were included in this network." (PMID 34247449, 2021). "Accordingly, the IDH1 inhibitor, ivosidenib, showed remarkable inhibitory effects on the cancer organoid in vitro." (PMID 33803322, 2021). "CpG islands at tumor suppressor and proapoptotic gene promoters are mostly hypermethylated in cancer cells due to DNMT overexpression or gene mutations (e.g., IDH1, SDH, TET2), which lead to uncontrolled division and growth of cells." (PMID 34199020, 2021). "Although there is a lack of comprehensive studies on broader metabolism in mutant IDH1/2 cancers, there have been numerous reports of elevated R-2-HG levels." (PMID 35028610, 2021). "Previous work from our lab and others have demonstrated that IDH1/2-mutant cancers are defective in homologous recombination (HR), which confer sensitivity to poly (ADP-ribose) polymerase (PARP) inhibitors." (PMID 34027408, 2021). "Mutations in isocitrate dehydrogenase (IDH1) and isocitrate dehydrogenase 2 (IDH2) represent a different group of cancer-related genetic alterations responsible for regulating the activity of α-ketoglutarate-dependent-dioxygenases." (PMID 34201149, 2021). "Since mutant IDH1/2 enzymes convert α-KG into 2-HG, cancer cells carrying these mutants should have alterations in the concentration of TCA cycle intermediates, and require substitution of energy sources to attenuate the deficiency of metabolic substrates." (PMID 34516556, 2021). "We review metabolic changes reported in the most common mutant IDH1/2 cancers in models that include cells lines, animal models with patient-derived xenografts (PDXs) and patient tissue biopsy (PTB) samples." (PMID 35028610, 2021). "Cancer related chromosomal translocations/deletions involving Chromosome region 2q34 (location of IDH1) and Chromosome region 15q26.1 (location of IDH2) are relatively rare." (PMID 34854890, 2021). "In agreement with its physiological function of regulating the intracellular NADP+/NADPH ratio, IDH1 plays an important role in metabolic adaption in physiology and cancer biology." (PMID 34440884, 2021). "Meanwhile, genes regulating DNA methylation, including DNMT1 and DNMT3A, the TET family and IDH1 and IDH2, are themselves frequently mutated in cancer and their mutation status is associated with changes to the cancer epigenome." (PMID 34871444, 2021). "The enzymes of TCA cycle, IDH1 and IDH2, are frequently mutated in glioblastoma multiforme and AML, thereby providing the clinical possibility to target these cancers." (PMID 33673109, 2021).
cancer (continued). "Separately, mutated forms of isocitrate dehydrogenase (IDH1 and IDH2) genes are known to be associated with aberrant DNA methylation in cancer." (PMID 34199020, 2021). "Metabolism dysregulation, e.g., the mutations of IDH1 and IDH2, can increase metabolites in cancer cells." (PMID 33920054, 2021). "IDH1 and IDH2 point mutations in cancer are heterozygous and occur most frequently at, or closely linked to, their active sites." (PMID 35028610, 2021). "We observed that JHU-083 induces growth inhibition in cancer cells irrespectively of IDH1/2mut status, likely due to additional intrinsic genetic and molecular differences between cell lines evaluated in our study." (PMID 33681764, 2021). "Further efforts are necessary to unravel the origin and the biological effects of 2-HG-lactone, which is likely to increase our understanding of tumorigenesis in IDH1/2-mutant cancers." (PMID 33916994, 2021). "For the common mutations of IDH1 and IDH2 found in cancer, intracellular and extracellular R-2-HG levels are substantially increased." (PMID 35028610, 2021). "In pan-cancer, the mutation status of the DDR genes was significantly associated with high TMB, excluding the IDH1 gene." (PMID 34198473, 2021). "As previously said, BTCs are known to harbor one of the highest frequencies of targetable molecular alterations across cancer types, including FGFR2 fusions or IDH1/2 mutations." (PMID 33805461, 2021). "Familial germline mutations in succinate dehydrogenase, and somatic mutations in isocitrate dehydrogenase 1 and 2 (IDH1 and IDH2), fumarate hydrase (FH) and isoforms of succinate dehydrogenase (SDH) are found in a variety of human cancers." (PMID 34631530, 2021). "Given the importance of these genes, we investigated the IDH1 and IDH2 mutations in a large series of cancer cases (n = 14,726) (solid malignancies) from the data of The Cancer Genome Atlas and the Memorial Slone Kettering Cancer Centre." (PMID 35996504, 2021). "These include known factors such as IDH1, as well as previously unreported genes, including four cancer driver genes (FGFR3, PPP6C, MAX, GNAQ)." (PMID 34944895, 2021). "Research in 2006 analysing cancer-associated mutations revealed an isocitrate dehydrogenase 1 (IDH 1) mutation in a colorectal cancer, leading to the R132C IDH1 variant." (PMID 34854890, 2021). "IDH1 and IDH2 genes are frequently mutated in some tumors and represent the metabolic genes most frequently mutated in human cancers." (PMID 32859092, 2020). "Cancer-associated mutations in IDH1 and IDH2 detected in a wide range of human cancers can result in neomorphic enzymes producing 2-HG, instead of α-KG, resulting in global epigenetic changes due to inhibition of JMJDs as well as TET enzymes." (PMID 32217072, 2020). "Recent advances in cancer genetics have found mutations in the isocitrate dehydrogenase 1 (IDH1) and 2 (IDH2) genes occur frequently in a variety of human cancers, including AML." (PMID 33409153, 2020). "The relative mRNA expression of IDH1 and other kinases in tested cancer cell lines, such as K562, U-251, HCT 116, MCF-7 and PANC-1, we determined using quantitative Real-Time PCR." (PMID 32110969, 2020). "IDH1 and IDH2 have been found mutated in multiple human cancers, rendering them as promising targets for anti-cancer therapy." (PMID 33114695, 2020). "Studies have proved that specific metabolic dependence in cancer was also the basis of effective treatment, including IDH1 inhibitors, folic acid and thymidine metabolism, lipid metabolism, and so on." (PMID 33424998, 2020).
cancer (continued). "Hotspots, recurrently mutated DNA positions in cancer, are thought to be oncogenic drivers because random chance is unlikely and the knowledge of clear examples of oncogenic hotspots in genes like BRAF, IDH1, KRAS and NRAS among many other genes." (PMID 32386297, 2020). "Links have been established between the patient's IDH1 or IDH2 mutation pattern, molecular mechanisms of the alternated epigenetic niche, and reprogrammed metabolism for predicting prognoses for various cancers." (PMID 31847543, 2020). "This score revealed ERGs with a high Multi-Omics Driver score in most cancer types (such as ATAD2) against those showing single driver score (such as IDH1, which has a high SNA driver score in LGG but relatively low CNA and expression driver scores)." (PMID 32963031, 2020). "IDH1 and IDH2, that produce α-ketoglutarate, can be present in mutated forms in many different kinds of cancers." (PMID 32328088, 2020). "In vitro studies have shown promising results using a NAMPT inhibitor in cancer cells, especially the IDH1/2 mutant cancer cell lines." (PMID 32111066, 2020). "These proof-of-concept studies indicate that targeting mutant IDH1/IDH2 has potential clinical application as a differentiation therapy to suppress cancer metastasis." (PMID 32839493, 2020). "Frequent mutations in the IDH1 and IDH2 genes have been shown in different types of cancer, including CCA." (PMID 32138158, 2020). "Mutated IDH1 and IDH2 are incapable of forming α-ketoglutarate and 2-hydroxyglutarate, thereby inhibiting TET protein activity and stimulating the development of cancer." (PMID 32328088, 2020). "IDH1 and IDH2 mutations decrease NADPH and GSH levels, leading to enhanced PI3K-AKT-mTOR signaling pathway activity and cancer cell migration." (PMID 32548570, 2020). "For each cancer cell type and/or situation, we should determine to what extent the side formation of 2HG by IDH1/2 and various other enzymes contributes to these “intermediate” levels." (PMID 31847543, 2020). "Isocitrate dehydrogenase 1 and 2 (IDH1 and IDH2) are two of the most frequently mutated metabolic genes in human cancer." (PMID 34766113, 2020). "We then took 1H scans of live mutant-IDH1 cancer cells (HT-1080, NHA mIDH1, SNU-1079 and COR-L105; for a full description of the cell types and mutations, see Methods)." (PMID 32587392, 2020). "In AML tumors, TET2 and IDH1/2 mutations are mutually exclusive, confirming that inhibition of TET2 is critical for mutant IDH1/2-driven cancer pathogenesis." (PMID 32764295, 2020). "It is noteworthy that such changes are more likely to occur in cancer stem cells of IDH1/2 mutant tumors." (PMID 31263678, 2019). "As expected, known cancer proteins BRAF, PIK3CA, KRas, Akt1, IDH1, and NRas showed the highest hotspot mutation scores in the TCGA dataset." (PMID 31345222, 2019). "In addition to the functional difference, we further explored whether there are topographic differences between chromosomes and chromosomal regions in addition to the functional variability in DNA methylation induced by IDH1/2 mutations common in all six cancer types." (PMID 31727977, 2019). "Because endogenous FASN is not required in most adult tissues and due to the specificity of the IDH1-dependent reductive carboxylation process in cancer cells, this mechanism is a highly attractive, cancer-specific target." (PMID 31676791, 2019). "Cancer-related mutations in IDH1 and IDH2 are mostly heterozygous and are always hotspot mutations involving arginine residues R132 in IDH1 and R140 or R172 in IDH2." (PMID 31139406, 2019). "Hotspot mutations in IDH1 and IDH2 have subsequently been shown to occur in at least 13 types of cancer, including 70% of malignant gliomas, 30% of AML and 5–25% of cholangiocarcinomas." (PMID 31795195, 2019).
cancer (continued). "Chromosomal arms 4q, 9p, 10p and 13q showed the highest ratio of hypermethylated enhancer probes across all IDH1/2 mutant cancers." (PMID 31727977, 2019). "Acquisition of hotspot mutations in IDH1 and IDH2 are key events in the development of various types of cancer." (PMID 31139406, 2019). "Mutations in IDH1 and IDH2 are found in different cancer types including brain tumor (over 70% of gliomas), colorectal cancer, prostate cancer and hematological malignancies as AML and myelodysplastic syndromes." (PMID 31234353, 2019). "Current clinical trials evaluating potential inhibitors in cancers with mutant IDH1/2 are aimed at confirming their safety and tolerability profiles, and clinical activity as a single agent or in combination with standard treatment strategies." (PMID 30857299, 2019). "Yet, preclinical studies with inhibitors of mutant IDH1 have shown variable effects on cancer progression, and it has been reported that 2-HG can inhibit glioma cell proliferation rather than enhance it." (PMID 31504662, 2019). "Hypermethylated common probes affect predominantly gene bodies while promoters in IDH1/2 mutant cancers remain unmethylated." (PMID 31727977, 2019). "The discovery of IDH1 and IDH2 mutations in several malignancies has brought to the approval of drugs targeting IDH1/2 mutants in cancers." (PMID 31010244, 2019). "Mutations in genes associated with key metabolic pathways (e.g., isocitrate dehydrogenase 1 and 2, IDH1/IDH2) are important drivers of cancer, including central nervous system (CNS) tumors." (PMID 30170631, 2018). "For example, the isocitrate dehydrogenase enzymes IDH1 and IDH2 function as RBPs [19•, 20••], and are strongly linked to cancer." (PMID 29216518, 2018). "Studies of Ohba and colleagues revealed that mutant IDH1 increases Rad51 mediated homologous recombination and further leads to temozolomide resistance in cancer cell lines." (PMID 29439493, 2018). "These oncometabolites are produced by mutations in the nuclear-encoded TCA enzymes, isocitrate dehydrogenase 1 and 2 (IDH1/2), succinate dehydrogenase (SDH), and fumarate hydratase (FH), and have been found in human cancers." (PMID 29342092, 2018). "These proof-of-concept studies indicate that targeting of mutant IDH1/IDH2 has potential clinical applications as a differentiation therapy in cancers bearing mutant forms of these proteins." (PMID 28092669, 2017). "Based on that; in certain tumors, IDH1 R132 and IDH2 R172 mutations are considered as driver ones, emphasizing the importance of targeting them as a cancer treatment therapy in those tumors." (PMID 28785398, 2017). "The roles of NADP-dependent IDH1 and 2 in normal cell and cancer metabolism are distinct from those of NAD-dependent IDH3." (PMID 28785398, 2017). "In our result, we also found BICD1 expression was significantly correlated with IDH1 expression, instead of the IDH1 mutant status, which suggested an emerging role of BICD1 in IDH1-mediated cancer metabolism." (PMID 29371945, 2017). "Mutations in other cancer genes including CBFB, IDH1, JAK1, KMT2A, SMAD4, and SMARCA4 were found in one MBC each." (PMID 29214215, 2017). "By contrast, IDH1 strongly favored positive associations in two cancer types, GBM and SKCM, consistent with reports that mutated IDH1 downregulates TET-dependent demethylation, resulting in aberrant CGI hypermethylation." (PMID 29125844, 2017). "IDH1/2-mutant cancers, which exhibit DNA hypermethylation, are sensitive to 5-azacytidine and 5-aza-2′-deoxycytidine." (PMID 28092669, 2017). "Isocitrate dehydrogenase 1 and 2 (IDH1 and IDH2) are key metabolic enzymes that are mutated in a variety of cancers to confer a gain-of-function activity resulting in the accumulation of an oncometabolite, D-2-hydroxyglutarate (2-HG)." (PMID 28986582, 2017). "Mutations in isocitrate dehydrogenase enzymes IDH1 (cytosolic) and IDH2 (mitochondrial) are highly frequent in glioma and AML, though rare in other cancers." (PMID 28373964, 2017).